CYBRD1 (cytochrome b reductase 1)
Description:
Plasma membrane reductase that uses cytoplasmic ascorbate as an electron donor to reduce extracellular Fe(3+) into Fe(2+). Probably functions in dietary iron absorption at the brush border of duodenal enterocytes by producing Fe(2+), the divalent form of iron that can be transported into enterocytes. It is also able to reduce extracellular monodehydro-L-ascorbate and may be involved in extracellular ascorbate regeneration by erythrocytes in blood. May also act as a ferrireductase in airway epithelial cells (Probable). May also function as a cupric transmembrane reductase (By similarity).
Synonyms: DCYTB; FRRS3; FLJ23462; CYB561A2
Tractability: Small molecule: a structure with a bound ligand is known. Antibody: UniProt places it where antibodies can reach, with high confidence; its Gene Ontology location is reachable by antibodies, with high confidence; UniProt predicts a signal peptide or a membrane-spanning region; the Human Protein Atlas places it where antibodies can reach.
Gene: Protein-coding gene on chromosome 2 (171,522,247 to 171,558,129, forward strand). Ensembl gene ENSG00000071967.
Subcellular location: Cell membrane; Apical cell membrane
Subcellular location (Human Protein Atlas): Plasma membrane
Pathways (Reactome):
Transport of small molecules: Iron uptake and transport
Gene Ontology:
Molecular function: identical protein binding; oxidoreductase activity, acting on metal ions; protein binding; transmembrane ascorbate ferrireductase activity; transmembrane monodehydroascorbate reductase activity; oxidoreductase activity
Biological process: ascorbate homeostasis; intracellular iron ion homeostasis; multicellular organismal-level iron ion homeostasis; reductive iron assimilation
Cellular component: apical plasma membrane; brush border membrane; extracellular exosome; membrane; plasma membrane
Genetic constraint (gnomAD): Loss-of-function variants: 14 observed, 23.26 expected, observed/expected ratio (o/e) 0.6, 90% interval 0.4 to 0.94. The upper end of that interval is the gene's LOEUF score, 0.94, which puts it in group 3 of 6, group 1 being the genes least tolerant of losing a copy. Missense variants: 328 observed, 372.36 expected, observed/expected ratio (o/e) 0.88, 90% interval 0.8 to 0.96. Synonymous variants: 146 observed, 144.86 expected, observed/expected ratio (o/e) 1.01, 90% interval 0.88 to 1.16.
Homologues: Orthologues: chimpanzee CYBRD1 (99% identical), macaque CYBRD1 (94% identical), pig CYBRD1 (84% identical), rabbit CYBRD1 (80% identical), rat Cybrd1 (76% identical), dog CYBRD1 (75% identical), mouse Cybrd1 (75% identical), tropical clawed frog cybrd1 (65% identical), guinea pig CYBRD1 (54% identical), zebrafish cybrd1 (53% identical), Drosophila melanogaster CG1275 (34% identical). Paralogues in human: CYB561A3 (36% identical), CYB561 (34% identical).
Diseases named in the same sentence as CYBRD1 in open-access papers:
CYBRD1 is named in the same sentence as 34 diseases in open-access papers, as found by Europe PMC text mining. Sharing a sentence is not in itself a finding about the gene and the disease. The quoted sentences say what the papers report.
iron deficiency (13 papers, 2007 to 2025). "They suggest that prolonged exposure to Cd may exacerbate iron deficiency, leading to anemia, and that HCP1 and Cybrd1 may be key factors in Cd-induced iron deficiency." (PMID 38612636, 2024). "LPS increased CYBRD1 (p < 0.001) and IL8 (p = 0.004) and tended to elevate TLR4 and TNF expression (p ≤ 0.07), while iron deficiency upregulated IL8 expression (p < 0.001)." (PMID 41295277, 2025). "Thus, it is suggested that HCP1 and Cybrd1 may be key factors in Cd-induced iron deficiency." (PMID 37505606, 2023). "Compared with other key roles in iron homeostasis (such as in activating CYBRD1), we found that TFRC, and IRP2 upregulation, and FTH1 downregulation were significantly induced after incubation with the miR-17-5p inhibitor in a degree of iron deficiency." (PMID 31423010, 2019). "This notion was subsequently challenged by Gunshin and colleagues with the observation that Cybrd1−/− (i.e., DCYTB-knockout) mice did not develop iron deficiency on a standard lab diet, or develop greater iron-deficiency on an iron-deficient diet, compared to wild-type mice." (PMID 25835049, 2015). "The lack of a 3′ UTR IRE, as found in Slc11a2, therefore allows Cybrd1 levels to be up-regulated via HIF-2α under both copper and iron deficiency." (PMID 23555700, 2013).
breast carcinoma (10 papers, 2016 to 2026). "For example, increased expression of plasma membrane-localized CYBRD1 is associated with favorable prognosis and is implicated in cancer cell proliferation and apoptosis in patients with breast cancer." (PMID 34594380, 2021). "However, other studies showed that high CYBRD1 expression has been associated with increased metastasis- and/or relapse-free survival in breast cancer." (PMID 32211330, 2020). "Notable examples include D2HGDH in lung tissue for asthma, CYBRD1 in breast mammary tissue for breast cancer, and CCR6 in spleen tissue for rheumatoid arthritis." (PMID 42201988, 2026). "Further, CYBRD1 is expressed at higher levels in tumors of patients with breast cancer than those of normal tissues, and high levels of CYBRD1 play a role in prolonging survival by inhibiting FAK activation." (PMID 34594380, 2021). "Higher CYBRD1 expression predicted prolonged metastasis-free and relapse-free survival in patients suffering from breast cancer." (PMID 34326882, 2021). "Moreover, upregulation of CYBRD1 mRNA was observed in breast cancer cell lines MCF, T-47D, BT-474, and ZR-75–30, as well as in prostate cancer cell line DU-145 with approximately 2- to 7-fold induction." (PMID 34326882, 2021). "In breast cancer, four Fe homeostasis genes (namely CYBRD1/DCYTB, LTF, STEAP1, and STEAP2) had significantly reduced expression levels in metastasis compared to primary tumors." (PMID 33255972, 2020). "Expression of TBC1D9 and CEACAM6 was higher in GATA3 mutant MCF-7 cells, GATA3 mutant CAMA1 cells, and primary GATA3 mutant breast cancer cells, whereas expression of PPT1, CYBRD1, HOXC13, and AFF3 was higher in GATA3 wild type cells." (PMID 29262572, 2017). "Furthermore, there have been no reports on the activity of CLIP4, CAPN2, CRLF1, CYBRD1, PHF10, and TRHDE in breast cancer or chemoresistance, thus making them new candidates for understanding breast cancer, the EMT, and chemoresistance." (PMID 27094684, 2016).
ovarian carcinoma (6 papers, 2014 to 2025). A malignant neoplasm originating from the surface ovarian epithelium. "Although few studies have documented the association of CYBRD1 with ovarian cancer, the evidence suggests that CYBRD1 can treat ovarian cancer." (PMID 38987777, 2024). "High expression of CYBRD1 was associated with pathological stage, distant metastasis, lymph node metastasis and other pathological data of ovarian cancer." (PMID 38355446, 2024). "The results showed that CYBRD1 was associated with immune infiltration in ovarian cancer." (PMID 34594380, 2021). "Bioinformatic analysis revealed that NDRG1, CYBRD1, and MT2A expressions upregulated and were associated with poor prognosis of ovarian cancer patients in the platinum-based treatment group, whereas upregulation of ERBB4 and ANK3 correlated with improved prognosis." (PMID 38987777, 2024). "Additionally, the study identifies photofrin as a potential CYBRD1-targeted drug for cisplatin-resistant ovarian cancer patients." (PMID 38987777, 2024). "Additionally, a meta-analysis of single-gene prognostic biomarkers in ovarian cancer revealed a correlation between high CYBRD1 expression and poor prognosis." (PMID 38987777, 2024). "Moreover, we prove a correlation between CYBRD1 and clinicopathological variables and draw survival curves to analyze the correlation between CYBRD1 expression with OS in patients with ovarian cancer from Shanghai East Hospital (EH)." (PMID 34594380, 2021). "The remaining genes among these down-regulated candidates have no previous association with ovarian cancer: Gpr64, Gpr126, Cybrd1, Star, Ncf2." (PMID 24672774, 2014). "The expression of CYBRD1, LRP2, TFRC, SLC22A17, HEPH, SLC39A14, and PCBP2 involved in iron import was associated with poor OS of ovarian cancer, whereas the expression of LCN2, CP, SLC46A1, STEAP3, and LTF in this process was associated with improved OS in ovarian cancer." (PMID 38186569, 2023). "In addition, in vitro experiments showed that NDRG1, CYBRD1, and MT2A played a role in ovarian cancer cisplatin resistance." (PMID 38987777, 2024). "Notably, cell experiments were performed to validate the roles of NDRG1, CYBRD1, and MT2A in cisplatin resistance in ovarian cancer." (PMID 38987777, 2024).
anemia (5 papers, 2015 to 2024). A reduction in the number of red blood cells, the amount of hemoglobin, and/or the volume of packed red blood cells. "Indeed, a recent study has demonstrated that copper deficiency leads to anemia, duodenal hypoxia, and the up-regulation of HIF2α and HIF2α-regulated iron absorption genes in mice (e.g., Cybrd1, Dmt1 and Fpn1)." (PMID 25835049, 2015).
colorectal cancer (5 papers, 2012 to 2025). A primary or metastatic malignant neoplasm that affects the colon or rectum. "When applied to colorectal cancer, we identified a missense polymorphism in iron-absorption gene CYBRD1 that associated with disease in individuals of English, but not Scottish, ancestry." (PMID 23236349, 2012). "The role of CYBRD1 in iron absorption is of particular interest given that many studies have investigated the link between dietary iron intake and the risk of colorectal cancer." (PMID 23236349, 2012). "CYBRD1 SNP rs884409 (, D′ = 1.0 with rs10455) has also been associated with serum ferritin levels and CYBRD1 is over-expressed in colorectal cancers." (PMID 23236349, 2012). "CYBRD1 appears to bind quercetin which has been posited as a chemopreventive agent for colorectal cancer." (PMID 23236349, 2012). "DDX17 reduces the 3’-UTR binding of miR-149-3p to CYBRD1 by down-regulating miR-149-3p, which in turn increases CYBRD1 expression and intracellular iron levels, and ultimately promotes EMT process and metastasis of colorectal cancer cells." (PMID 41322492, 2025).
ovarian serous cystadenocarcinoma (2 papers, 2021 to 2024). A malignant serous cystic epithelial neoplasm arising from the ovary. "Cytochrome b reductase 1 (CYBRD1) promotes the development of ovarian serous cystadenocarcinoma (OV)." (PMID 34594380, 2021). "A study helmed by Chen and collaborators underscored that CYBRD1, potentially indicative of ovarian serous cystadenocarcinoma (OV), witnessed pronounced elevations in OV, with its surges linked to factors like lymphatic dissemination, disease progression, and clinical trajectories less favorable." (PMID 39702158, 2024).
bladder cancer (1 paper, 2021). "We further investigated these genes using the Oncomine database, and the results also indicated lower expression of PDE5A, RECK, ZEB2, and CYBRD1 in bladder cancer tissue than in normal bladder mucosa." (PMID 33987019, 2021). "Further analysis of gene expression from the GEO dataset indicated lower expression of PDE5A, RECK, ZEB2, and CYBRD1 in bladder cancer tissue than in normal bladder mucosa, which indicated that PDE5A, RECK, ZEB2, and CYBRD1 may act as tumor suppressors in UTUC." (PMID 33987019, 2021).
dengue (1 paper, 2023). "CYBRD1 can potentially be a classifier between DHF and DSS in the late acute phase, and to the best of our knowledge, it has not been previously associated with dengue." (PMID 37638052, 2023).
glioblastoma (1 paper, 2021). The most malignant astrocytic tumor (WHO grade IV). "It was found that high levels of ENSG00000203739 or ENSG00000271646 expression could potentially suppress miR-637 and promote the expression of possible oncogene CYBRD1, thus promoting the proliferative and invasive capacities of glioblastoma." (PMID 34326882, 2021). "Data sets from Gene Expression Omnibus (GEO), CGGA-RNAseq, and The Cancer Genome Atlas Glioblastoma Multiforme (TCGA-GBM) were analyzed, and an increased expression of Cytochrome B Reductase 1 (CYBRD1) was identified and could be associated with aggravated clinical outcomes." (PMID 34326882, 2021).
glioma (1 paper, 2021). A benign or malignant brain and spinal cord tumor that arises from glial cells (astrocytes, oligodendrocytes, ependymal cells). "According to the Kaplan–Meier curves, higher CYBRD1 expression was associated with poorer overall survival in patients with glioma based on TCGA-GBMLGG." (PMID 34326882, 2021). "Online data mining was performed to confirm the expression status of CYBRD1 during glioma development." (PMID 34326882, 2021). "CYBRD1 overexpression in glioma cell lines was enhanced, whereas CYBRD1 silencing attenuated the aggressiveness of glioma cells." (PMID 34326882, 2021). "Herein, IFN-α treatment dramatically suppressed the viability, migratory ability, and invasive ability of glioma cells, whereas CYBRD1 overexpression attenuated IFN-α-induced inhibition upon the aggressiveness of glioma cells." (PMID 34326882, 2021). "In order to get a better understanding of the oncogenic role of CYBRD1 in glioma, CYBRD1 co-expression genes were identified by making use of data from TCGA-GBMLGG." (PMID 34326882, 2021). "According to TCGA-GBMLGG, the expression of CYBRD1 showed to be dramatically upregulated within high-grade glioma tissue samples compared with low-grade glioma tissue samples." (PMID 34326882, 2021). "CYBRD1 overexpression in glioma cell lines is enhanced, whereas CYBRD1 silencing attenuated the aggressiveness of glioma cells." (PMID 34326882, 2021). "Consistently, CYBRD1 mRNA expression is shown to be dramatically upregulated within glioma tissue samples and increased with an increasing grade." (PMID 34326882, 2021). "According to IVY-RNAseq, CYBRD1 expression was upregulated in recurrent glioma tissues compared with that in primary glioma tissues." (PMID 34326882, 2021). "In IFN-α-treated glioma cells, IFN-α considerably repressed the viability, migratory ability, and invasive ability of glioma cells, whereas CYBRD1 overexpression attenuated the effects of IFN-α treatment on glioma cell aggressiveness." (PMID 34326882, 2021). "Higher levels of CYBRD1 in recurring or high-grade gliomas suggest its role in carcinogenesis and development." (PMID 34326882, 2021). "CYBRD1 overexpression enhances glioma cell aggressiveness and attenuates glioma cell response to IFN-α." (PMID 34326882, 2021). "According to TCGA-GBM, CYBRD1 expression was upregulated in recurrent glioma tissues (n = 13) compared to those in primary glioma tissues (n = 154)." (PMID 34326882, 2021). "It was confirmed that CYBRD1 was abnormally upregulated within glioma; CYBRD1 overexpression or silencing was achieved in glioma LN229 and T98G cells to investigate its specific effects on cell phenotype." (PMID 34326882, 2021). "In this study, the abnormal upregulation of CYBRD1 in high-grade and recurrent gliomas was reported by bioinformatics and experimental analyses." (PMID 34326882, 2021). "It is therefore suggested that higher CYBRD1 expression predicts a poorer prognosis in glioma patients." (PMID 34326882, 2021). "According to CGGA-RNAseq-693, CYBRD1 expression was upregulated in recurrent glioma tissues compared to those in primary glioma tissues." (PMID 34326882, 2021). "Herein, the study first found that CYBRD1 overexpression within glioma cells significantly promoted cell viability, migration, and invasion." (PMID 34326882, 2021). "The potential of CYBRD1 as a biomarker for glioma prognosis was subsequently examined using online data." (PMID 34326882, 2021). "Herein, this study confirmed the abnormal upregulation of CYBRD1 in high-grade and recurrent gliomas." (PMID 34326882, 2021). "On the contrary, CYBRD1 silencing in glioma cells inhibited glioma cell aggressiveness by repressing cell viability, migratory ability, and invasive ability." (PMID 34326882, 2021). "In conclusion, CYBRD1 could potentially serve as a biomarker for glioma recurrence; in other words, higher CYBRD1 expression might be a predictor of earlier recurrence." (PMID 34326882, 2021).
glioma (continued). "Glioma patients with higher CYBRD1 expression significantly predicted shorter survival, suggesting that CYBRD1 might be considered a marker possibly involved in the recurrence and prognosis of gliomas." (PMID 34326882, 2021). "In other words, higher CYBRD1 expression might be correlated with more aggressive glioma cell phenotypes." (PMID 34326882, 2021). "The online data indicate that CYBRD1 expression is abnormally upregulated in recurrent glioma tissues, suggesting that it could be considered a marker that is possibly involved in glioma recurrence." (PMID 34326882, 2021). "These in vitro findings showcase the oncogenic effect of CYBRD1 overexpression on glioma." (PMID 34326882, 2021). "Glioma patients with higher CYBRD1 expression predicted poorer survival." (PMID 34326882, 2021). "Our present findings suggest that higher CYBRD1 expression might be correlated with more aggressive glioma cell phenotypes and a predictor of earlier recurrence." (PMID 34326882, 2021). "The data indicate that glioma cells could harbor a more aggressive phenotype due to CYBRD1 overexpression." (PMID 34326882, 2021). "Furthermore, the specific effects of CYBRD1 upon the phenotype of glioma cells were subsequently determined." (PMID 34326882, 2021). "CYBRD1 could potentially serve as a biomarker for glioma recurrence." (PMID 34326882, 2021). "Therefore, CYBRD1 expression level might be a potential biomarker for earlier recurrence and a promising target for glioma therapy." (PMID 34326882, 2021). "Therefore, the effects of CYBRD1 on interferon-stimulated glioma cells were examined." (PMID 34326882, 2021). "In IFN-α-treated glioma cells, IFN-α suppressed the viability and migratory ability and invasive ability of glioma cells, whereas CYBRD1 overexpression attenuated the antitumor effects of IFN-α." (PMID 34326882, 2021). "As shown by the RT-PCR analysis, only CYBRD1 mRNA levels were significantly upregulated in glioma tissues compared to the nonglioma normal tissues." (PMID 34326882, 2021).
liver disease (1 paper, 2023). "Especially it would be interesting to verify the link between hepatic expression of co-inhibitory receptors, genetic variation in HDAC3 and CYBRD1, and liver disease progression to HCC." (PMID 37632052, 2023). "Further studies are needed to determine the significance of HDAC3 and CYBRD1 in liver disease progression to HCC in CHC patients." (PMID 37632052, 2023).
lung carcinoma (1 paper, 2021). "Studies of the expression and functional activation of CYBRD1 were proposed because CYBRD1 mediates the transport of ferric ion in lung cancer cells and is involved in mitochondrial metabolism." (PMID 34594380, 2021). "CYBRD1 mediates direct electron transfer, instead of transport and diffusion across the membrane, and may therefore facilitate energy reprogramming in lung cancer epithelial cells." (PMID 34594380, 2021).
mesothelioma (1 paper, 2025). A usually malignant and aggressive neoplasm of the mesothelium which is often associated with exposure to asbestos. "By intersecting high-risk genes with upregulated DEGs, we identified four key high-risk genes associated with mesothelioma: MPZL1, SOAT1, TACC3, and CYBRD1." (PMID 40223054, 2025).
mucopolysaccharidoses (1 paper, 2021). "GSEA demonstrated that mucopolysaccharidoses, the butyrophilin BTN family, the EGFR/SMRTE pathway, IRF3- mediated induction of type I INF, FOXO-mediated transcription of cell cycle genes, and the ERK pathway were differentially enriched in association with high levels of CYBRD1 expression." (PMID 34594380, 2021).